LRP1B (LDL receptor related protein 1B)
Diseases named in the same sentence as LRP1B in open-access papers (continued):
Sharing a sentence is not in itself a finding about the gene and the disease.
tumor (continued). "LRP1B is a tumor suppressor with decreased expression in several primary cancers and is among 10 most significantly deleted genes across 3312 cancer samples." (PMID 27047539, 2016). "It has been reported that chromosomal, epigenetic and microRNA-mediated inactivation of LRP1B increases the growth and invasive capacity of tumor cells." (PMID 26840027, 2016). "Taken together, these findings demonstrate that, consistent with the postulated tumor suppressor function, overexpression of full-length Lrp1b leads to impaired cellular proliferation, while LRP1B knockdown has the opposite effect." (PMID 27626682, 2016). "The specific deletion of LRP1b in certain tumors through genetic and epigenetic silencing suggests a role as a tumor suppressor." (PMID 20383322, 2010). "One mouse tumor was found to contain an internal deletion of exons of the Lrp1b gene, which led to a smaller in-frame transcript." (PMID 20942901, 2010). "Strikingly, the observed rate of homozygous deletions within LRP1B in human cancer cell lines is equivalent to or higher than known recessive tumor-suppressor genes such as PTEN, RB1 and SMAD4 in the same cell line dataset." (PMID 20942901, 2010). "Our results indicate that LRP1B may function as a tumor suppressor factor in CRC, playing a significant role in mutation, therapy, and immune infiltration." (PMID 40170839, 2025). "Importantly, further analysis of variant combinations in the tumor showed that co-occurrence of KRAS and LRP1B variants significantly improved OS (p = 0.003) and merged PFS (p = 0.008)." (PMID 40011914, 2025). "Similarly, mutations in CSMD3, LRP1B, and PCLO are closely associated with tumor development and progression." (PMID 41235252, 2025). "However, the high E2F group presented increased frequencies of ABCA13, LRP1B, and ATP10B missense/nonsense mutations, suggesting a potential link between E2Fs and tumor-suppressor gene alterations." (PMID 40599792, 2025). "Furthermore, single-cell sequencing analysis revealed that LRP1B expression was predominantly low in tumor immune cells, falling below the expression cutoff." (PMID 40170839, 2025). "One tumour possessed a KIAA1549::BRAF fusion alongside VEGFR2, MSH6, and LRP1B variants." (PMID 39948623, 2025). "However, in the process of chemotherapy, how LRP1B inhibits tumor development is unclear and needs further study." (PMID 40184130, 2025). "Although previous research has focused mainly on the tumor suppressor function of LRP1B, its effect on immunotherapy remains unclear." (PMID 39660409, 2024). "Tumor 5 contained an integration within the LRP1B gene, with few LRP1B transcripts detected." (PMID 38898085, 2024). "We identified 4 genes using stringent criteria, and while none were mutated in more than 1 tumor, interestingly, 2 genes were previously shown to be mutated in human tRCC: Blm and Lrp1b." (PMID 38386415, 2024). "Furthermore, LRP1B allele frequency was negatively correlated with the top 1% CDR3 sequences (r = -0.55, p = 0.033) and positively correlated with tumor shrinkage (r = 0.68, p = 0.007)." (PMID 38840771, 2024).
tumor (continued). "Additionally, we aimed to gain a deeper understanding of the potential crosstalk between LRP1B and the tumor microenvironment by evaluating the secretome of GB LRP1B-altered cells." (PMID 37511044, 2023). "In addition, the endocytic activity of LRP1B plays a role in the crosstalk between tumor cells and the microenvironment, as a secretome modulator, and influences cellular processes such as angiogenesis and metastasis." (PMID 37511044, 2023). "Immunohistochemical analysis demonstrated higher expression of LRP1B in tumor tissues." (PMID 38054797, 2023). "Interestingly, these cells also overexpress LRP1B, contrary to most of the established tumor cell lines." (PMID 37511044, 2023). "The expression of RNF43 and LRP1B correlated significantly with tumor type according to Lauren, i.e., both were significantly reduced in diffuse type GC, adding them to an increasing list of WNT pathway components, which are differentially mutated and expressed in diffuse and intestinal type GC." (PMID 36823311, 2023). "The effects of LRP1B silencing, or of polyploidy itself, on tumor cell growth are still debatable and may be dependent on the cellular context." (PMID 37511044, 2023). "In our study, we further evaluated the effect of LRP1B silencing on tumor growth." (PMID 37511044, 2023). "More interestingly, serial tumor profiling also allowed us to identify a panel of mutated genes enriched and present at baseline and persisting through the end of CRT including FBXW7, LRP1B, and RYR2." (PMID 36201462, 2022). "The inactivation of LRP1B may also bring about the alteration of the tumor microenvironment that could confer the increased tumor growth and enhanced tumor invasion ability." (PMID 35150083, 2022). "However, the latest update from the Network of Cancer Genes (NCG 6.0) listed LRP1B as a potentially false‐positive tumor suppressor." (PMID 35486034, 2022). "This study will explore LRP1B mutation and its effects on HCC patients and analyze the gene mutation status and the infiltration of immune cell in the tumor immune microenvironment and the relationship between gene mutation status and immune checkpoint gene expression by bioinformatics analysis." (PMID 34093808, 2021). "Firstly, the correlation between LRP1B mutation and tumor HPV status was lack of molecular evidence and underlying mechanisms in the interaction process." (PMID 33994859, 2021). "Regardless of the existing limitations (already referred) to study the impact of LRP1B expression in tumor cells, several studies using tumor cell lines (and some using their xenografts in nude mice) have contributed to the knowledge on the role of LRP1B in cancer known so far." (PMID 34577535, 2021). "LRP1B is a tumor suppressor that interacts with uPAR to inhibit cell migration." (PMID 33432021, 2021). "In our results, the expression status of LRP1B was identified as a biomarker for normal and neoplasm samples of CC and HNSCC, with AUC 0.8007 in HNSCC and 0.9024 in CC, which suggested that LRP1B could serve as a biomarker in CC and HNSCC." (PMID 33994859, 2021).
tumor (continued). "Nevertheless, LRP1B could still play a role in tumor progression as several studies link its downregulation through deletion and carcinogenesis." (PMID 32224864, 2020). "LRP1B mutations have been associated with treatment response to immune-checkpoint blockade independent of tumor type." (PMID 33106165, 2020). "LRP1B is a tumor suppressor and may regulate cell motility via the RhoA/Cdc42 pathway and actin cytoskeleton reorganization, but the exact role of LRP1B in HCC development has not been reported." (PMID 29117265, 2017). "In NSCLC cells with low/absent endogenous LRP1B levels overexpression of full-length mLrp1b or a LRP1B minireceptor resulted in marked inhibition of cellular proliferation compared to empty vector transfected cells, strongly supporting the proposed tumor suppressor function." (PMID 27626682, 2016). "Taken together, these observations strongly suggest a role of LRP1B in tumorigenesis and strengthen the original hypothesis of the receptor serving as a tumor suppressor." (PMID 27626682, 2016). "LRP1B is therefore considered as a putative tumor suppressor." (PMID 27626682, 2016). "Given that constitutive activation of Stat3 is a frequent aberrancy in cancer cells that is supposed to directly contribute to tumorigenesis, the observed activation of Stat3 in A427 cells overexpressing the proposed tumor suppressor Lrp1b appears contradictory." (PMID 27626682, 2016). "The exact mechanistic role of LRP1b in tumor suppression and development has remained elusive." (PMID 20383322, 2010). "Meanwhile, LRP1B may function as a tumor suppressor factor in CRC." (PMID 40170839, 2025). "LRP1B may stimulate tumor immune cell infiltration to provide GC patients with survival benefits." (PMID 38136305, 2023). "LRP1B induced tumor immune cell infiltration, which may improve the outcomes of GC patients." (PMID 38136305, 2023). "We assumed that LRP1B might play a tumor-promoting role in HCC progression." (PMID 35389768, 2022). "GATA4 and LRP1B were tumor suppressor genes, which might be related to the resistance of olaparib." (PMID 33432021, 2021). "To date, eight interacting partners of the LRP1B intracellular domain have been identified which are involved in several biological processes such as signal transduction, synaptic transmission and plasticity, cell migration, tumorigenesis and tumor progression, and DNA damage response." (PMID 34577535, 2021). "To verify the differential expression status between CDK6 and LRP1B in patients with (study group) or without (control group) mutations, we performed IHC staining on tumor tissues from 36 and 34 patients, who were screened and matched using tNGS, from the CDK6 and LRP1B groups, respectively." (PMID 34152098, 2021). "Finally, we showed that LRP1B expression was significantly down-regulated in PC tissues relative to matched adjacent non-tumor tissues, showing that increased miR-500 expression may be the result of LRP1B inhibition in PC." (PMID 30877185, 2019). "The influence of histone genes on tumor developments might be supported by the eQTLs identified in the current study, because some of the eQTLs were located within anticipated tumor suppressor genes such as low-density lipoprotein receptor-related protein (LRP1B) and utrophin (UTRN)." (PMID 28929106, 2017).
tumor (continued). "Future research will have to address these mechanisms in more detail and is required to determine whether the growth-suppressing effect of LRP1B extends from the inhibition of tumor cell growth to a possible role of LRP1B in other cells, as e.g. the formation of atherosclerotic lesions." (PMID 27626682, 2016). "Therefore, LRP1B was postulated as a putative tumor suppressor." (PMID 27626682, 2016). "When we overexpressed SLC7A11 in LRP1B knockdown cell lines, we rescued tumor cells from erastin‐induced ferroptosis, whereas knocking down SLC7A11 in LRP1B knockdown cell lines restored the sensitivity of tumor cells to erastin‐induced ferroptosis." (PMID 39660409, 2024). "Overexpression of LRP1B increased the expression of SLC7A11 and inhibited the increase of lipid ROS and MDA induced by Erastin in tumor cells." (PMID 39660409, 2024). "Among these genes, CDKN2A, CDKN2B, CUX1, LRP1B and PTPRD were retrieved as tumor suppressors from the TSGene database." (PMID 38831459, 2024). "Reducing LRP1B expression resulted in decreased SLC7A11 expression, as well as elevated levels of Lipid ROS and MDA induced by erastin in tumor cells." (PMID 39660409, 2024). "In Tumor 5, HPV16 DNA was integrated into the LDL receptor-related protein 1B (LRP1B) gene on chromosome 2." (PMID 38898085, 2024). "In order to fill this gap of information, we explored the tumor biological significance of RNF43 and LRP1B in a large and extensively characterized cohort of therapy-naive GC by immunohistochemistry." (PMID 36823311, 2023). "In this study on a large and well-characterized cohort of GC patients, we explored the putative tumor biological significance of RNF43 and LRP1B." (PMID 36823311, 2023). "LRP1B, a member of the LDL receptor family of lipoprotein receptors, has recently been proposed as a putative tumor suppressor, with functions related to cell cycle arrest and modulation of cell migration/spreading." (PMID 36230748, 2022). "High LRP1B expression was shown to be related to poor outcomes and the determination of HCC patients’ tumor stage." (PMID 35389768, 2022). "LRP1B belongs to the gene family of low-density lipoprotein (LDL) receptor, which plays multi-roles as a tumor suppressor gene in normal cell function and development." (PMID 33994859, 2021). "In contrast, mutant BRAF, ATM, LRP1B, FAT4, FMN2, TRRAP, and ROS1 had higher stromal score (except ATM), immune score and ESTIMATE score, and the tumor purity was lower than the wild-type." (PMID 33836681, 2021). "We selected LRP1B and TCF4 (ITF2) genes that were completely deleted in the same tumor type or at least three of the four cell lines, respectively." (PMID 32224864, 2020). "LRP1B, a member of the low density lipoprotein (LDL) receptor family, is identified as a new candidate tumor suppressor gene." (PMID 30877185, 2019). "Tumor volume was strongly correlated with the CN amplifications of subclone 1–ERBB4, LRP1B, PTPRD, and EPHA5 CN all exhibited r ∈ [0.76,0.79] and p-value ∈ [4.8e-4, 9.4e-4]." (PMID 30560892, 2018). "The upregulation of LRP1B, RGS5, STAT2, and HLA-A in SDR42E1-depleted cells suggests enhanced apoptotic singling, tumor-immune crosstalk, and immune recognition—aligning with vitamin D’s immunomodulatory roles and potentially increasing chemotherapy sensitivity." (PMID 40756515, 2025).
tumor (continued). "Although variants rs10166768 (C>G) with LRP1B and rs200093832 within TRPM3 reached a p-value below the significance threshold only in the PTC tumor samples and not the PTC blood samples compared to the 1KGP controls, MAFs did not suggest somatic mutations." (PMID 39770638, 2024). "Positive LRP1B expression in TCs was correlated with PD-L1, but not with age, tumor location, histological type, Lauren type, TNM stage, HER-2, TMB, or microsatellite status." (PMID 38136305, 2023). "However, despite their putative tumor biological role, data on the expression of RNF43 and LRP1B in GC are scarce." (PMID 36823311, 2023). "LRP1B expression in TCs stimulates the infiltration of CD4+ and CD8+ T cells and raises the ratio of CD86/CD163, which may be due to an increase in tumor immunogenicity to achieve immune activation and prevent disease progression." (PMID 38136305, 2023). "Tumor stage classification did not highlight a subgroup with a better correlation between LRP1B expression and patient prognosis (data not shown)." (PMID 35841413, 2022). "Multivariate COX analysis showed that LRP1B mutation remained to be significantly associated with better PFS, which was independent of PD-L1, bTMB, tumor size, and CRP level." (PMID 35902848, 2022). "Using the RNA-seq data, we showed that feature S(1,−1)SumAverg was associated with expression levels of genes (i.e. LRP1B and PITX2) in tumour tissue but not in adjacent normal tissue." (PMID 36050449, 2022). "In total, recurrent (>3) MEI were observed in 329 protein-coding genes of which 28 genes are annotated in the Cancer Gene Consensus with either oncogenic (ALK1, ERBB4, TSHR, PREX2, CTNNA2, CTNND2) or tumour suppression roles (EBF1, LRP1B, PTPRD, GPC5, ROBO2, PTPRT)." (PMID 35301290, 2022). "We found that MACROD2, RBFOX1, and LRP1B were frequently affected by SVs in Chinese patients with HCC, suggesting that SVs in those genes might play a role in tumor development and progression." (PMID 32257385, 2020). "In the TM00099 tumor, subclone 1 dominated the non-cisplatin xenografts (70% of cells on average, as interpolated from the LRP1B CN values) while the cisplatin-treated xenografts had reduced levels of subclone 1 (43% of cells on average)." (PMID 30560892, 2018). "Considering RNF43 and LRP1B as tumor suppressors only, does not seem to be sufficient." (PMID 36823311, 2023). "Conversely, we found the previously identified PCa driver gene LRP1B (12/17) and new candidate genes TTC28 (16/27), CADM2 (12/16), LSAMP (11/16), EYS (16/18), PTPRD (12/18), PACRG (5/6) and PDE4D (12/17) to be predominately interrupted in tumours from African patients." (PMID 36045381, 2022). "Previously reported mechanisms of action for LRP1b, including the regulation of the urokinase (uPAR) and platelet-derived growth factor (PDGF) receptor trafficking at the membrane level, overlap with the functions of expressed and unmutated LRP1 in tumor tissues." (PMID 20383322, 2010). "RNF43 and LRP1B are not easy to use prognostic or predictive biomarkers in GC and might require the simultaneous analysis of several members of the Wnt signaling pathway in relation to histological tumor type." (PMID 36823311, 2023). "LRP1B and ROBO2 are tumor suppressors, but FGF13, MAST4 and SPHKAP have not been associated with cancer development." (PMID 29117265, 2017). "On the other hand, two genes recently proposed to be tumor suppressors based on their focal deletion in cancer, PDE4D and LRP1B, are amongst the top ten most frequently affected CFS-like genes and accordingly may not be functional tumor suppressors." (PMID 23805207, 2013).